BRCA1 (BRCA1 DNA repair associated)
Diseases named in the same sentence as BRCA1 in open-access papers (continued):
Sharing a sentence is not in itself a finding about the gene and the disease.
cancer (continued). "Many of the germline mutations associated with cancer development are concentrated in the amino terminal RING domain and the carboxyl terminal BRCT motifs of BRCA1, which are the most well-characterized regions of the protein." (PMID 24832651, 2013). "All 6 “late-onset” (>50 years) BRCA1 samples was however correctly classified while the 3 misclassified BRCA1 samples were all early-onset cancers (40–42 years)." (PMID 23704984, 2013). "Nonetheless, fewer than 50% of patients with BRCA1/2-mutant cancers respond to these drugs, raising important questions about identifying patients most likely to derive benefit from PARP inhibition." (PMID 24062981, 2013). "In this study, we show that BRCA1 activates the Notch pathway in breast cells by transcriptionally upregulating Notch ligands and receptors in both normal and cancer cells." (PMID 23863842, 2013). "The most striking feature of TopBP1 is that it has eight BRCA1 C-terminal (BRCT) domains which were first identified in breast cancer gene 1 (BRCA1)." (PMID 23277395, 2013). "The angiogenesis, through the expression of VEGF, HIF-1α, and MVD plays an important role supporting the aggressive nature of BRCA1-2 carrier cancers." (PMID 23326384, 2013). "In BRCA1-2 carrier cancers the expression was homogeneous with most of the cells strongly immunoreactive for VEGF." (PMID 23326384, 2013). "Treatment of cancer cell lines with 5-Aza causes the reactivation of hypermethylated VHL, MLH1 and BRCA1." (PMID 23341493, 2013). "Simulations comparing normal to BRCA1-mutant breast tissue demonstrated rates of invasive cancer development similar to published epidemiologic data with respect to both cumulative incidence over time and estrogen-receptor status." (PMID 23704974, 2013). "It has been demonstrated in an “in vitro” study that the BRCA1 protein blocked VEGF promoter activity by ERα, which explains the VEGF expression increase in BRCA1 mutated cancers." (PMID 23326384, 2013). "Impaired HR in human cancer cells depleted of BRCA1 using a similar HR reporter has also been observed." (PMID 23388117, 2013). "For instance, in the study upregulation of DNA repair gene – BRCA1 was observed in cancer as compared to normal cervix." (PMID 24403257, 2013). "The integrated analysis identified the top 30 significant genes (P<0.01), which comprised genes associated with cancer, whereas the protein-protein interaction analysis indicated a strong association between FANCA and BRCA1." (PMID 23483937, 2013). "It should be mentioned that some other interesting data published in the previous years approve the ability of DIM to stimulate BRCA1 expression in non-cancer diseases such as inflammatory bowel diseases and heart failures caused by oxidative stress." (PMID 24325835, 2013). "The idea of using the unique genetic profile of tumor cells relative to somatic cells to selectively kill cancer has been applied by various groups, such as in the case of the chemical-genetic interaction between BRCA1/2 and PARP inhibitors." (PMID 23382697, 2013). "There have also been case reports of rare cures achieved in BRCA1/2 carriers with ovarian and other cancers following other, older treatments such as melphalan." (PMID 23522120, 2013). "Some of the most paradigmatic examples of cancer genes such as BRCA1, BRCA2, NF1, and ATM are included in these two sets." (PMID 24204383, 2013). "Such women are more likely to have explored their own family cancer histories, either informally or as part of the genetic counseling and BRCA1/2 testing process." (PMID 23660117, 2013). "Although, promoter methylation of p16, DAPK, GSTP1 and BRCA1 genes are frequent events in several carcinomas, including ESCC, but very few studies considered these genes together in ESCC." (PMID 23596512, 2013).
cancer (continued). "The recent therapeutic approaches towards BRCA1 carcinomas have increased the clinical utility of BRCA1 genetic analysis." (PMID 23586058, 2013). "Expression of BRCA1 was found to be about two-fold lower in sporadic triple-negative breast cancers compared to estrogen receptor (ER)-positive cancers." (PMID 23203101, 2012). "Although triple negative/basal-like (TN/BL) are sporadic tumors, they share many phenotypical, immunohistochemical, clinical and molecular characteristics with BRCA1/p220-mutant cancers." (PMID 22431556, 2012). "If confirmed, this observation offers opportunities for more efficient and less costly BRCA1/2 cancer screening." (PMID 22984553, 2012). "Importantly, when a BRCA1/2 mutation is identified in an individual, there is a 50% chance that first-degree relatives (eg, male and female children and siblings) have also inherited the mutation and may therefore face increased risks for cancer." (PMID 22257650, 2012). "Multiple cancer predisposition genes have already been identified in high-risk Utah pedigrees identified in the UPDB, including BRCA1, BRCA2, and p16/CDKN2A." (PMID 22471249, 2012). "Network 1 genes failed to separate the good and bad outcome groups, even though certain cell proliferation genes are known to be associated with these cancers, such as ASPM in GBM and BRCA1 and BRCA2 in OV." (PMID 22956898, 2012). "Transcriptional profiling followed by ChIP identified a subset of cellular genes that are regulated in a similar fashion to HIV-1 by Spt6 and/or PAAF1, including many that are involved in cancer, such as BRCA1 and BARD1." (PMID 22316138, 2012). "Recently PARP inhibitors have been shown to be highly effective in tumors with an underlying susceptibility to DNA damage, such as BRCA1 and BRCA2 mutation related cancers." (PMID 22768044, 2012). "Reconstitution of BRCA1 in the cells via transfection meant that BRCA1 functions were regained, and resulted in a reduced level of cancer cell death, following treatment with cisplatin or other DNA damaging agents." (PMID 23203101, 2012). "For cancer genes which have been reported to have somatic or germline mutations in EOC, 3 were found to harbor copy deletions in serous histotype: PIK3R1, BRCA1, and STK11." (PMID 23078675, 2012). "Up regulation of Abl and Brca1 genes specifically in cancer cells in contrast to that of the normal cells is a significant observation." (PMID 22321936, 2012). "Aberrant regulation of RAD21 by mir-299-5p is also supported by a comparison of 11 BRCA1 basal and 13 normal breast samples, in which a sevenfold reduction in mir-299-5p was observed between BRCA1 cancers and normal breast tissue (P = 0.0002)." (PMID 22537934, 2012). "When BRCA1/p220 expression and/or function are lost and AUF1 expression is dropped (e.g., in cancer cells), BRCA1-IRIS mRNA is perhaps stabilized by HuR." (PMID 22431556, 2012). "All tumors derived from BRCA1 or BRCA2 germline mutation carriers showed loss of wild-type haplotypes at 17q21 or 13q12, respectively, as expected of recessive cancer genes." (PMID 22608084, 2012). "Many other cancer-related genes such as Brca1 and Brca2 also show a strong co-expression with the Bc055324 gene." (PMID 23039964, 2012). "Inhibition of Cdk1 potentiates the sensitivity of cancer cells to PARP inhibitors by reducing BRCA1 recruitment and subsequent repair of DSBs." (PMID 22737296, 2012). "The other important genes in this pathway like Abl1, Gml, Brca1, Zak, Xrcc5, Trex1, Pms1, Ccnu and Apex2 were also up regulated in the cancer cells." (PMID 22321936, 2012).
cancer (continued). "Because BRCA1 and BRCA2 are involved in homologous recombination (HR)-based DSB repair, the elevated frequency of microhomology-mediated indels in BRCA1 or BRCA2 mutant cancers presumably reflects usage of alternative methods of DSB repair in these cancers." (PMID 22608084, 2012). "Recently, the interaction of two RAPTA compounds, RAPTA-C and carboRAPTA-C, with the specified DNA sequence of the human breast cancer suppressor gene BRCA1 has been studied." (PMID 23202946, 2012). "BRCA1 nuclear transport and ubiquitin E3 ligase enzymatic activity are tightly regulated by the BRCA1 dimeric binding partner BARD1 and further modulated by cancer mutations and diverse signaling pathways." (PMID 24278741, 2012). "BRCA1 cancers also have characteristic gene-expression and genomic profiles, and appear to be sensitive to DNA damage by cisplatinum." (PMID 22537934, 2012). "This further supports our argument that BRCA1 cancers behave differently from other cancers in response to RAD21 overexpression." (PMID 22537934, 2012). "Two important examples are provided by the cancer-related genes BRCA1 (breast cancer 1) and TGF-β (transforming growth factor β)." (PMID 22693426, 2012). "In this mini-review, we examine the structure-function relationships of the BRCA1 protein and the relevance to cancer progression." (PMID 22737296, 2012). "coli genes as well as two human cancer genes (BRCA1 and BRCA2) in three independent stages and different multiplexing folds on the SOLiD system." (PMID 22913592, 2012). "Their proportion varies during the cell cycle, between tissues and in cancer suggesting functional importance of BRCA1 splicing regulation around this exon." (PMID 22615956, 2012). "In contrast to luminal A cancers, CBP cancers occur more often among African Americans, BRCA1 mutation carriers and younger women, providing additional support for the view that these tumors are etiologically different." (PMID 22513288, 2012). "Firstly, we recognize that studying the mechanism of BRCA1 down regulation by an HDAC inhibitor exclusively in cancer cell lines provides limited data that requires further exploration in an in vivo model." (PMID 21854619, 2011). "If PARP activity is lost by using specific inhibitors, the formation of DNA lesions increases and, when this event is contemporary with deficiency of BRCA1 or BRCA2 proteins, a “synthetic lethality” situation occurs for the cancer cells." (PMID 21926946, 2011). "Mouse models have established an important role for BRCA1 in mammary gland development, emphasising the relationship between development and cancer." (PMID 23508738, 2011). "For women and families who are found to carry a variant of uncertain clinical significance (VUS) in either BRCA1 or BRCA2, screening recommendations are offered according to personal and family history of cancer." (PMID 22295226, 2011). "In all, 200 mg twice daily was selected for further study in BRCA1 or 2 mutation carriers, 19 of which had known BRCA-associated cancers, including breast, ovarian and prostate; 63% of these patients experienced clinical benefit." (PMID 21989215, 2011). "In a recent review, it has been noted that hRR is a useful biomarker in cancer therapy similar to BRCA1, and recent data has shown that hRR1 expression can be used as a useful biomarker for the selection of agents active in the treatment of cancer." (PMID 23115527, 2011). "Management decisions in BRCA1/2 carriers prophylactically or at the time of diagnosis of an invasive cancer are complex." (PMID 22295226, 2011). "Case report: major response of heavily pretreated metastatic BRCA1-related cancer to the combination of cisplatin and gemcitabine, with the duration > 6 months." (PMID 21819606, 2011).
cancer (continued). "The involvement of CTCF in cancer and in particular, in the epigenetic regulation of tumor suppressor genes, is further supported by recent data from other laboratories studying the BRCA1 and p16INK4a tumor suppressor genes, or even the apoptotic gene PUMA." (PMID 21663659, 2011). "Epidemiological study of BRCA1 and BRCA2 mutation carriers (EMBRACE): EMBRACE is supported by Cancer Research UK Grants C1287/A10118 and C1287/A11990." (PMID 21427728, 2011). "Perhaps the strongest evidence for the role of DNA repair in resistance to cisplatin is the somatic reversion of BRCA1 and BRCA2 mutations to DNA repair proficient proteins in chemotherapy-resistant cancers, initially treatment-sensitive." (PMID 21679440, 2011). "Evidences suggest that BRCA1 part of the "Role of BRCA1, BRCA2 and ATR in Cancer Susceptibility" pathway significantly enhances the ability of TNF-α or IFN-γ to activate transcription from the promoters of NF-κB target genes." (PMID 21226955, 2011). "One motivation to study them in these cancers is that BRCA1 is involved in many cellular processes as well as in repairing double-stranded DNA breaks (DSBs) mediated by homologous recombination (HR)." (PMID 22032724, 2011). "Pathologic features of BRCA1 ER+ cancers were compared to those of BRCA1 ER- cancers and to age-matched ER+ sporadic cancers." (PMID 20149218, 2010). "Since BRCA1 cancers are so often ER-, it has been suggested that ER negativity is intrinsic to BRCA1 cancers and reflects the cell of origin of these tumors." (PMID 21080930, 2010). "The study group of 80 BRCA1 cases was compared with 320 matched sporadic cases from the Modena cancer registry which were the same age, and had the same tumour grade and stage." (PMID 20219108, 2010). "It is thought that the BRCA1 and BRCA2 proteins function in many tissues to repair DNA damage, so the limited cancer causation to breast and ovary remains a mystery." (PMID 20111735, 2010). "ER+ BRCA1 cancers that retained wt BRCA1 were significantly more likely than those that lost wt BRCA1 to have a low mitotic rate (odds ratio (OR), 5.16; 95% CI, 1.91 to ∞)." (PMID 21080930, 2010). "Compared with ER+ sporadic cancers, ER+ BRCA1 cancers were more often of pure invasive ductal type (P = 0.03), more often had a high mitotic rate (>10 mitoses per 10 HPF, P = 0.03) and demonstrated a more limited spectrum of histologic types." (PMID 20149218, 2010). "They do, however, share with the women in families in which a BRCA1 or BRCA2 mutation has been identified a fear of a new cancer and the overwhelming experience that comes along with that cancer." (PMID 20180951, 2010). "One of the strengths of this study is that the pathologic features of all cancers in this study, both BRCA1 and control, were reviewed by two dedicated breast pathologists (SJS and LCC)." (PMID 20149218, 2010). "BRCA1 and BRCA2 proteins are implicated in DNA double strand break (DSB) repair and loss of BRCA function results in chromosomal instability, hence to cancer predisposition." (PMID 20735817, 2010). "The recent discovery that PARP-1 inhibitors kill BRCA1/2 deficient cells with a high level of specificity subsequently opens up a potential therapy which looks very hopeful for BRCA1 cancer patients." (PMID 20961453, 2010). "Clinically important mutations in BRCA1 and BRCA2 genes and cancer incidence in relatives from Estonia." (PMID 20380699, 2010). "Toward this end, a detailed immunophenotypic and molecular analysis of the ER+ BRCA1 cancers is currently underway." (PMID 20149218, 2010). "When compared to sporadic ER+ cancers, ER+ BRCA1 cancers were more often of invasive ductal type (RR 2.4, P = 0.03), with a high mitotic rate (RR 5.0, P = 0.006) and absent or mild lymphocytic infiltrate (RR 10.2, P = 0.04)." (PMID 20149218, 2010). "Results above indicate that BRCA1 protein is methylated in both cancer cell lines and patient samples." (PMID 20614009, 2010).
cancer (continued). "Most of these differences remained significant even when limiting the comparison to histologic grade 3 BRCA1 ER+ and ER- cancers." (PMID 20149218, 2010). "In univariate analysis, those ER+ BRCA1 cancers retaining wt BRCA1 more often had a low mitotic rate (100% vs 27%; P < 0.001), were less often of pure ductal histology (50% vs 85%; P = 0.05), and less often grade 3 (0% vs 68%; P < 0.001)." (PMID 21080930, 2010). "As BRCA1 cancers are so often ER-, it has been suggested that ER negativity is intrinsic to BRCA1 cancers and reflects the cell of origin of these tumors." (PMID 20149218, 2010). "Inherited mutations also often produce a limited set or tissue type of cancer such as BRCA1 or BRCA2 with breast and ovarian tumors." (PMID 20111735, 2010). "Inherited susceptibility genes, BRCA1 and BRCA2, are considered in breast, ovarian and other common cancers etiology." (PMID 20579331, 2010). "Members of hereditary breast/ovarian cancer (HBOC) families who have been affected by cancer are offered testing for mutations in the BRCA1 and BRCA2 cancer predisposition genes with the hope of identifying the cause of the family's cancers." (PMID 20180951, 2010). "These ER+ cancers appear pathologically "intermediate" between ER- BRCA1 cancers and ER+ sporadic breast cancers raising the possibility that either some ER+ BRCA1 cancers are incidental or that there is a unique mechanism by which these cancers develop." (PMID 20149218, 2010). "Our findings further confirm that mutation frequency for BRCA1 and BRCA2 as cancer susceptibility genes for breast-ovarian carcinoma needs to be evaluated in each distinct geographical area." (PMID 19619314, 2009). "Our observations sheds light on a possible previously uncharacterized mechanism of breast carcinogenesis mediated by XIST misbehaviour, particularly in BRCA1-related cancers." (PMID 19440381, 2009). "Germ-line mutations in the BRCA1 and BRCA2 genes confer a high lifetime risk of developing breast and other cancers." (PMID 19920816, 2009). "The observation in this study of a positive association of HIF-1α with high tumour grade and relapse-free survival supports a similarly upregulated hypoxic response in BRCA1/basal like cancers." (PMID 19724277, 2009). "As expected, there was a significant association between the presence of BRCA1 or BRCA2 mutations and the occurrence of cancer; p<0.0001." (PMID 19329713, 2009). "A seminal phase I trial has provided evidence that olaparib is well tolerated, inhibits PARP activity in surrogate samples and also in tumor samples and exerts activity against BRCA1/2 related cancer." (PMID 19825178, 2009). "There are published reports of genetic modifiers of cancer risk in mutation carriers (for example, variants in AIB1 in BRCA1; variants in RAD51, FGFR2 and MAP3K1 in BRCA2; and variants in TNRC9 in BRCA1 and BRCA2)." (PMID 19843326, 2009). "The uptake for additional psychological support was significantly higher in women with a proven BRCA1 or BRCA2 mutation (91% vs 67%; p = 0.03), and tended to be higher in women with experience of death due to cancer of a sister (23% vs 2%; p = 0.07)." (PMID 19338651, 2009). "With respect to tumor stage, the results were encouraging for early detection; most occult cancers in BRCA1 carriers were still at an early stage, either CIS, stage I, or stage II." (PMID 19636370, 2009). "Epidemiological study of BRCA1 and BRCA2 mutation carriers (EMBRACE): EMBRACE is supported by Cancer Research UK Grants C1287/A10118 and C1287/A8874." (PMID 19920816, 2009). "The two classes (sometimes referred to as "phenotypes" although they refer to properties of germline DNA) are BRCA1-mutant cancers and non-BRCA1 cancers, with sample sizes 25 and 93, respectively." (PMID 19695104, 2009).